MET (MET proto-oncogene, receptor tyrosine kinase)
Diseases named in the same sentence as MET in open-access papers (continued):
Sharing a sentence is not in itself a finding about the gene and the disease.
glioma (continued). "In glioma cells, for example, HGF drives c-MET to the periplasm of the endosome for prolonged activation of Rac1, resulting in optimum membrane ruffling, cell motility, and invasion." (PMID 35630066, 2022). "In the same time, miR-155, miR-410, and miR-181a/b correlated negatively with WNT5A, MET, and EGFR in plasma of high-grade glioma patients." (PMID 35646622, 2022). "Signaling through the hepatocyte growth factor receptor (c-MET) and the midkine (ALK ligand) promotes gliomagenesis and glioma stem cell maintenance, contributing to the resistance of glioma cells to anticancer therapies." (PMID 35625997, 2022). "Latest reports have shown that these miRNAs by regulation PDCD4, WNT5A, MET, and EGFR also serves certain biological function in the progression of various human tumors including glioma." (PMID 35646622, 2022). "The relative protein expression of MES markers MET and YKL-40 and the PN marker OLIG2 was detected in four different human glioma cell lines." (PMID 34381734, 2021). "The presence of these MET-fusions triggered MAPK stimulation and, when present in tumors with deregulated cell cycles, gave rise to aggressive glial tumors in an in vivo model." (PMID 34055785, 2021). "Similar to findings with TKIs, preclinical studies of cetuximab noted failure to alter EGFR downstream signal transduction in the context of gliomas, with reduction in cell viability achieved after inhibiting PI3K and MET pathways." (PMID 33187135, 2020). "Here we demonstrate that glioma organoids and PDOXs accurately maintain distinct genetic backgrounds of parental tumors, including gene amplifications of EGFR, PDGFRA, MET, MDM2/4, and CDK4/6, which are difficult to derive and preserve in vitro." (PMID 33009951, 2020). "In this study, 47.6% of glioma patients were detected ctDNA including 1p/19q, MDM2, ERBB2, IDH1, CDKN2A, CDK4, PDGFRA, CCNE1, MET." (PMID 32973641, 2020). "According to the Chinese Glioma Genome Atlas (CGGA) database and the qRT-PCR results, we found that MET expression levels were higher in recurrent GBM samples than in primary GBM samples." (PMID 31053733, 2019). "NRP1 interacts with MET and increases the ability of HGF to stimulate pancreatic carcinoma cell invasion along with the proliferation and survival of gliomas." (PMID 30871059, 2019). "Multiple growth factor receptors including MET and EGFR are known to be overexpressed in aggressive gliomas." (PMID 31595389, 2019). "SGX-523 is a small molecule inhibitor of HGFR/MET tyrosine kinase activity that inhibits tumour cell growth, migration and invasion in a panel of glioma cells in vitro and reduced tumour growth in a murine xenograft model of GBM using the U87MG GBM cell line." (PMID 31616641, 2019). "The mesenchymal subtype in glioma is defined by a genomic and transcriptomic profile, notably by higher expression levels of mesenchymal markers such as CHI3L1/YKL40 and MET." (PMID 30333910, 2018). "These MET fusions activated MAPK signaling and, in cooperation with other molecular abnormalities compromising cell cycle regulation, induced aggressive glial tumors." (PMID 30279357, 2018). "Since TGF-β2 induces ERK phosphorylation in a U0126-sensitive manner in glioma cells, we next explored a role for ERK in controlling the HGF/c-MET pathway." (PMID 29238047, 2017). "Using genetic and pharmacological approaches to stimulate or antagonize the TGF-β pathway in human glioma-initiating cells (GIC), we observed that TGF-β exerts an inhibitory effect on c-MET phosphorylation." (PMID 29238047, 2017).
glioma (continued). "Given their role in mediating migration and invasiveness, resistance to irradiation and maintenance of the glioma SC pool, both HGF/c-MET and TGF-β signaling pathways have been considered as potential therapeutic targets." (PMID 29238047, 2017). "Further, the protein expression of hepatocyte growth factor (HGF), the ligand for c-MET, was found to positively correlate and be co-expressed with MMP-2 in human glioma." (PMID 28234925, 2017). "It negatively regulates stem cell-like characteristics of glioma cells through downregulating c-Met and NOTCH and inhibits the growth, invasion and metastasis of GC by targeting PDGFR and MET." (PMID 27644439, 2016). "RMPAhigh gliomas were also enriched in the expression of ERBB2, FGFR1 and MET (and its ligand HGF), DDR2 (a receptor for activated collagen fibers), as well as the WNT co-receptors ROR1 and RYK." (PMID 27385209, 2016). "In the RMPAlow gliomas, a different set of RTK signaling-related genes including MET (8.9%), EPHA1 (8.9%), EPHB6 (8.9%), EPHB4 (8.3%), BRAF (8.9%), FGF6 (11.9%), FGF23 (11.9%), NTF3 (11.9%), and ANGPT1 (9.5%) were amplified." (PMID 27385209, 2016). "Amplifications and mutations of PDGFRA, KIT and KDR were found in 8-15% of RMPAhigh gliomas, followed by EPHB3 (7.7%), FGFR1 (5.9%), FGFR3 (5.9%) and MET (4.1%)." (PMID 27385209, 2016). "The ODA14 tumour was selected after quantitative PCR screening of a series of gliomas for amplification of the EGFR,MET,MYC and PDGFRA genes, which are known to be recurrently amplified in these tumours." (PMID 25378339, 2014). "In glioma cells, autocrine activation of c-MET by HGF-c-MET increased basal levels of c-MET phosphorylation at tyrosine (Tyr) 1003." (PMID 21283737, 2011). "Two recent studies independently demonstrated that NRP1 physically binds c-MET, and potentiates c-MET activation in response to HGF stimulation in human glioma and pancreatic cancer cells." (PMID 20085644, 2010). "Notably, NTRK- and ALK-driven tumors formed a cluster separate from MET- and ROS1-driven gliomas, indicating systematic differences between these two groups with similar oncokinases." (PMID 41381884, 2026). "Similarly, PDGFR-A amplification is characteristic of the proneural GBM subtype, while MET amplification and PDGFR overexpression also contribute to glioma pathogenesis." (PMID 41514664, 2026). "Importantly, in pediatric gliomas, gene fusions involving anaplastic lymphoma kinase (ALK), ROS proto-oncogene 1 (ROS1), neurotrophic tyrosine receptor kinase (NTRK2) and MET define a distinct, hemispheric high-grade subgroup with intermediate prognosis." (PMID 41514664, 2026). "Capmatinib + BEV was well-tolerated but had no clear signal of activity in c-MET non-activated high-grade glioma." (PMID 39925637, 2025). "Some of these gliomas feature alterations in genes such as ROS1, ALK, MET, and NTRK1–3." (PMID 41155159, 2025). "Among pediatric CNS neoplasms, MET gene fusions have to this day exclusively been reported in the context of infantile high-grade gliomas, while a distinctive enrichment in hemispheric tumors has been observed and recurrent MET gene fusions as PTPRZ1::MET have been reported." (PMID 38902810, 2024). "Recent advances yielded remarkable responses of NTRK or ALK fusion pHGG to selective inhibitors, especially in IHG, but there is currently no effective selective therapy demonstrated for MET fusion-positive glioma." (PMID 38849845, 2024). "Another highly selective MET inhibitor, bozitinib (also known as PLB-1001 or vebreltinib), exhibits blood–brain barrier permeability and has shown effective inhibition of MET-driven glioma progression in both cell lines and xenograft models." (PMID 39598385, 2024).
glioma (continued). "Yet, at concentrations known to specifically inhibit MET phosphorylation, tepotinib failed to sensitize glioma cells to the inhibitory effects of irradiation in vitro." (PMID 36915128, 2023). "Glioma cell viability or proliferation are unaffected by genetic or pharmacological MET inhibition using tepotinib or CRISPR/Cas9-engineered Met gene knockout and MET inhibition fails to sensitize glioma cells to irradiation in vitro." (PMID 36915128, 2023). "To determine whether ME2 promotes PMT of glioma cells, we performed a western blot assay to detect the expression of MES markers MET, YKL40, N-cadherin, and vimentin; epithelial marker E-cadherin; and PN marker OLIG2." (PMID 34381734, 2021). "This method could be used as the “gold standard” of ZM positive (ZM+) glioma diagnosis as the fusion point of PTPRZ1 and MET could be confirmed via Sanger sequencing included in this method." (PMID 33645009, 2021). "Before we finally certified the glioma samples as ZM+, all the PCR product bands on agarose gel were purified and sequenced via Sanger sequencing followed by confirmation of the fusion point of PTPRZ1 and MET fragments." (PMID 33645009, 2021). "The results showed that ME2 overexpression in SW1783 and U251MG cells upregulated the expression of N-cadherin, vimentin, YKL40, and MET expression, whereas it downregulated the expression of E-cadherin and OLIG2, suggesting that ME2 promotes PMT of glioma cells." (PMID 34381734, 2021). "Glioma-related ctDNAs included 1p/19q, MDM2, ERBB2, IDH1, CDKN2A, CDK4, PDGFRA, CCNE1, MET." (PMID 32973641, 2020). "Moreover, the ctDNAs in the metastatic brain tumors included ALK and MDM2, and glioma-related ctDNAs included 1p/19q and MDM2 followed by frequencies of ERBB2, IDH1, CDKN2A, CDK4, PDGFRA, CCNE1, MET." (PMID 32973641, 2020). "It exerts an effect as a tumor suppressor in glioma, possibly by a negative downregulation of the MET pathway but not AKT." (PMID 31842352, 2019). "Our current study presents a new hypothesis wherein neuron-type NHE5 ectopically expressed in C6 glioma cells plays a critical role in MET, EGFR, and integrin signaling in glioma." (PMID 31595389, 2019). "In comparison to IDHmut gliomas, IDHwt gliomas have greater activation of receptor tyrosine kinase signaling through EGFR gain, MET gain, and BRAF gain, in addition to increased gains in cell cycle activators and losses of cell cycle inhibitors compared to IDHmut gliomas." (PMID 26091668, 2015). "U138MG cells expressed high levels of MET on mRNA and protein levels, whereas LN-308 glioma cells demonstrated almost no MET expression (left)." (PMID 25682871, 2015). "Aberrant phosphotyrosine-based signaling is a hallmark of cancer, and gliomas are no exception; tyrosine kinase membrane receptors like EGFR, ERBB2, PDGFRA, MET and VEGFR2 have been implicated in glioma growth, angiogenesis and cell motility." (PMID 25238264, 2014). "Nine novel functional miRNAs (hsa-miR-129, -136, -145, -155, -181b, -342-5p, -342-3p, -376a/b) in GBM cell lines were validated for their importance in glioma cell growth, and similar effects for six target genes (ROCK1, RHOA, MET, CSF1R, EIF2AK1, FGF7) of these miRNAs were shown functionally." (PMID 23577178, 2013). "Additionally, the classification now recognizes infant-type hemispheric glioma as a separate high-grade glioma category characterized by a unique molecular profile, including fusion genes involving ALK, ROS1, NTRK1/2/3, or MET, predominantly seen in newborns and infants." (PMID 38137148, 2023). "Consequently, the expression of circulating miR-155, miR-410, and miR-181a/b and its putative gene-targets PDCD4, WNT5A, MET, and EGFR had a strong inverse relation in high-grade glioma, thereby suggesting that the potential roles of miR-155, miR-410, and miR-181a/b in oncogenesis of glioma tumors." (PMID 35646622, 2022).
glioma (continued). "Moreover, miR-155, miR-181a/b and miR-410 may participate in the molecular mechanism of high-grade glioma by interaction PDCD4, WNT5A, MET, and EGFR." (PMID 35646622, 2022). "In gliomas, c-MET and MMP-2 may share several properties promoting tumor survival, angiogenesis, and invasion, and in fact similar to MMP-2, cells with strong c-MET expression were found in blood vessels and perinecrotic areas." (PMID 28234925, 2017). "Interestingly, miR-340 did not influence the MET protein level in a panel of glioma cell lines." (PMID 25831237, 2015). "Interestingly, MET+, but not MET− cells proved to be difficult to expand ex vivo and exhibited a significantly lower sphere-induction potential when compared to control cells, implying the dependency of these cells on the glioma microenvironment for self-renewal." (PMID 41339360, 2025). "Finally, autocrine loops characterized by the co-expression of MET and HGF by the same cell are frequently found in non-epithelial tumors and in gliomas." (PMID 38892318, 2024).
lung adenocarcinoma (212 papers, 2008 to 2025). A carcinoma that arises from the lung and is characterized by the presence of malignant glandular epithelial cells. "It is also essential to distinguish MET amplification from MET exon 14 (METex14)-skipping mutations, which occur in 3% to 4% of lung adenocarcinomas." (PMID 39941826, 2025). "MET exon 14 skipping mutations—which occur in approximately 3–4% of lung adenocarcinomas—are now effectively treated with MET tyrosine kinase inhibitors such as capmatinib, tepotinib, and savolitinib." (PMID 41303058, 2025). "Previous reports have shown associations between MET overexpression and many types of cancers, including colorectal carcinoma, ovarian cancer, and lung adenocarcinoma." (PMID 40004241, 2025). "Of note, MET amplification should be distinguished from MET exon 14 (METex14) mutation, which occurs as a de novo alteration in 3% to 4% of lung adenocarcinomas." (PMID 36765799, 2023). "We report the case of an 81-year-old male patient with lung adenocarcinoma with a MET exon 14 skipping mutation who was treated with chemoimmunotherapy and achieved a durable response." (PMID 37007311, 2023). "The potential for sequential use of combinatorial therapy of osimertinib and cabozantinib has also been demonstrated in a case study where a patient with EGFR-mutated lung adenocarcinoma acquired four MET mutations upon crizotinib treatment." (PMID 36698189, 2023). "This case report provides treatment strategies for epidermal growth factor receptor tyrosine kinase inhibitors (EGFR-TKIs)-untreated lung adenocarcinoma patients simultaneously carrying MET alterations and EGFR exon 20 insertion mutations." (PMID 35739536, 2022). "We also confirmed this observation in another lung adenocarcinoma cell line with inducible MET expression that we generated starting from the KRAS-mutated A549 cell line." (PMID 34298655, 2021). "MET exon 14 skipping mutations occur in 3–4% of lung adenocarcinomas and results in the deletion of the intracellular juxtamembrane domain of the receptor, leading to enhanced signaling and tumor proliferation." (PMID 33510214, 2021). "Recently, mutations in exon 14 of MET that lead to an in‐frame deletion of the negative regulatory juxtamembrane domain were identified in 4% of lung adenocarcinomas." (PMID 31040125, 2019). "Recently, a lung adenocarcinoma patient with MET amplification developed resistance to dual anti-EGFR/MET therapy due to an acquired METD1228V mutation." (PMID 28968967, 2017). "More recently, several large series assessing the genomic landscape of lung adenocarcinoma reported MET exon 14 skipping mutations to occur in approximately 3% of all tumors and 2% of other lung neoplasms." (PMID 28418914, 2017). "Low expression of miR-206 and high levels of MET were strongly associated with the poor cisplatin sensitivity of lung adenocarcinoma patients." (PMID 27014910, 2016). "Amplification of the c-MET gene is present in about 4% of lung adenocarcinomas and is usually associated with a poorer prognosis." (PMID 26371045, 2015). "Crizotinib as well as cabozantinib, a TKI which inhibits c-MET, VEGFR2, have shown some early activity in lung adenocarcinomas with MET mutations." (PMID 26371045, 2015). "A recent report demonstrated that lung adenocarcinoma cases with a co-existence of positive MET FISH status and EGFR mutation had shorter disease-free survival (DFS) as well as OS after resection." (PMID 25886066, 2015). "The MET exon 14 alterations occur at a similar frequency as U2AF1 mutations in lung adenocarcinoma (TCGA, submitted)." (PMID 24498085, 2014).